AR (androgen receptor)
Diseases named in the same sentence as AR in open-access papers (continued):
Sharing a sentence is not in itself a finding about the gene and the disease.
prostate carcinoma (continued). "Fibroblasts and keratinocytes express AR during wound healing, and stromal AR may play opposite roles in different stages of prostate cancer, either blocking or promoting prostate cancer metastasis." (PMID 21359179, 2011). "PEITC perturbs AR signaling pathway by down regulating AR transcription through the inhibition of the AR gene promoter (Sp1) expression and inducing AR protein degradation in androgen-dependent (AD) and androgen-independent (AI) prostate cancer LNCaP cells." (PMID 22069601, 2010). "Androgen receptor (AR) is the most relevant signaling pathway in prostate cancer, and is presently considered a significant drug target, since its inhibition has demonstrated to be important for prostate cancer prevention and treatment." (PMID 22069601, 2010). "Moreover, Wnt-11 and AR are co-expressed in other prostate cancer cell lines and in prostate tumour cells." (PMID 20219091, 2010). "Quantitation of epithelial cell nuclei displaying either no AR expression or very low staining revealed a significant increase in the number of cells with altered AR expression in prostate carcinomas from Men1 mutant mice compared with normal Men1+/+ prostate glands." (PMID 20663219, 2010). "Altogether, genes with functional categories that were enriched in expression trends may be consistent with the AR signaling pathway playing a role in progression of prostate cancer to castration-recurrence." (PMID 20868494, 2010). "Pim1 has been reported to modulate androgen receptor signaling in prostate cancer cells." (PMID 20515470, 2010). "Moreover, AR signaling remains a central target even for castrate-resistant metastatic prostate cancers." (PMID 20628607, 2010). "Nearly 70% of clinical prostate cancer cases are AR positive." (PMID 20663219, 2010). "Furthermore, LEF1 was identified as a potential marker for androgen-independent disease and as a key regulator of androgen receptor expression and prostate cancer growth and invasion." (PMID 21190562, 2010). "Very recently, a stimulatory effect of FKBP51 on AR has been reported in prostate cancer cells." (PMID 20661446, 2010). "In addition, hypoxia has been shown to increase androgen receptor sensitivity and androgen receptor induced expression of the human PSA gene in a prostate cancer cell line." (PMID 20663134, 2010). "Prostate cancer cells can be subdivided based upon AR protein status and response to castration." (PMID 20628607, 2010). "We thus investigated if BFA might inhibit proliferation of androgen-responsive prostate cancer LNCaP cells and also explored how it would be carried out, focusing on cell cycle and androgen receptor (AR)." (PMID 20102617, 2010). "It is likely that RU486 may also affect other prostate cancer cell types as well, as double AR mutant metastatic prostate cancer cells containing substitutions of L701H and T877A have been found that use cortisol as a growth factor." (PMID 20946663, 2010). "To extend our study to this clinical scenario, we next examined the effect of the c-Met inhibitors in LNCaP, an AR positive androgen sensitive prostate cancer line, and LNCaP C4-2, an androgen-insensitive subline, derived from LNCaP cells grown in a castrated host." (PMID 20946682, 2010). "The estrogen receptor α subunit is expressed in androgen receptor-dependent prostate cancer, suggesting that the ER pathway may be involved in prostate cancer." (PMID 20659312, 2010). "Also since the promoter of this gene exhibits strong androgen receptor-specific and tissue-specific regulation, Pbsn is proposed to be a potential candidate for targeted therapies for advanced prostate cancer." (PMID 20540791, 2010). "However, it is important to note that when compared to other commonly used AR-expressing prostate cancer cell lines (i.e., LNCaP, LNCaP C4-2B, LAPC4), the levels of AR protein expressed by E006AA cells is approximately five- to ten-fold lower." (PMID 20628607, 2010).
prostate carcinoma (continued). "The presence of AR expression, somatic AR mutations or amplification does not necessarily mean, however, that a prostate cancer cell is addicted to AR signaling." (PMID 20628607, 2010). "Additionally, an inverse correlation between the expression of AR and c-Met has been observed in prostate epithelium and prostate cancer cell lines." (PMID 20946682, 2010). "Importantly, when AR is then ectopically expressed in such AR-independent prostate cancer cells, androgen-activated AR signaling inhibits cell growth." (PMID 20628607, 2010). "Interestingly, the cysteine-rich domain of sFRP1 interacted with Frizzled receptors expressed in prostate cancer cells, suggesting that sFRP1/Frizzled complexes activate a signal that leads to repression of AR." (PMID 19277043, 2009). "Indeed, the progression of prostate cancer despite the administration of ADT is more a reflection of the ineffectiveness of current treatments than the disease gaining genuine autonomy from AR-signalling pathways." (PMID 19223900, 2009). "However, the function of AR in normal prostate epithelial cells in vivo is anti-proliferative, whereas AR has proliferative function in prostate cancer." (PMID 19277043, 2009). "Alternatively, as we used charcoal-stripped serum, which still has about 10% of androgens remaining in the serum, it may suggest that low levels of androgen can still activate a large number of genes through AR in the advanced prostate cancer cell PC3." (PMID 19668381, 2009). "With the aim of validating the usefulness of our method, our proposed prediction model with fewer false positives was applied to the PubChem Compound database in order to predict the potential ligands for the “androgen receptor”, which is one of the genes responsible for prostate cancer." (PMID 19503826, 2009). "Similar results were observed using LNCaP, another AR-expressing prostate cancer cell line." (PMID 19277043, 2009). "We showed that AR could be activated in low androgen or ligand independent manner in advanced prostate cancer cell line PC3 cells expressing the AR." (PMID 19668381, 2009). "Androgen receptor (AR) is an essential component in androgen-dependent prostate cancer." (PMID 19383165, 2009). "Because the sFRP1 CRD competes with Frizzled receptors for binding to Wnts, we hypothesised that sFRP1 represses AR by antagonising autocrine Wnt signals in prostate cancer cells." (PMID 19277043, 2009). "Androgen receptor (AR) is likely a crucial factor in prostate cancer progression." (PMID 19855844, 2009). "Furthermore, few studies have investigated the crosstalk between AR and IL-6 secreted in an autocrine manner in prostate cancer cells." (PMID 19844233, 2009). "Because both AR transcriptional activity and the cytoplasmic and/or nuclear levels of β-catenin are elevated in prostate cancer, crosstalk between AR and Wnt/β-catenin signalling pathways may contribute to prostate cancer progression." (PMID 19277043, 2009). "In addition, there are also some other pathways have been inferred, such as the arachidonic acid metabolism pathway and androgen receptor signalling pathway, which are also very critical in prostate cancer progression." (PMID 19640296, 2009). "Reciprocally, using transient transfections of prostate cancer cells lines, we explored whether the AR overexpression had any effect on the Wnt/β-Catenin signaling pathway." (PMID 18218096, 2008). "Here we show that the AR can potentiate Wnt signaling in prostate cancer cells." (PMID 18218096, 2008). "Since WT1 activates the AR promoter in prostate cancer cells, this suggests that WT1 may directly or indirectly regulate PSA gene expression." (PMID 18631392, 2008). "Vav3 also potentiates EGF activity for cell growth and AR activation in prostate cancer cells." (PMID 18518979, 2008). "This decreased expression of AR in higher grade tumors may indicate a more poorly differentiated cell type or, as in prostate cancer, a transition to an androgen-independent state." (PMID 18433501, 2008).
prostate carcinoma (continued). "Since the expression of Ebp1 correlated with prostate cancer progression, we also evaluated whether the expression of Ebp1 correlated with the nuclear expression of Ebp1 regulated proteins (AR, Cyclin D1 & ErbB3) and the proliferation marker Ki67." (PMID 19025630, 2008). "In addition, the simultaneous activation of the Wnt signaling pathway and overexpression of the AR promote prostate cancer cell growth and transformation at castration levels of androgens." (PMID 18218096, 2008). "Based on these results, mAR may be a novel target that can be used for the selective elimination of mAR+ prostate cancer cells independently of the functional status of the intracellular androgen receptor." (PMID 19055752, 2008). "In our study we have observed that high levels of nuclear AR staining and β-Catenin staining may co-localize in prostate cancer cells." (PMID 18218096, 2008). "Finally, our laboratory has demonstrated that ectopic expression of Ebp1 results in decreased expression of AR and AR target genes and inhibition of growth of prostate cancer cells both in vivo and in vitro." (PMID 19094237, 2008). "This raises the possibility of increasing androgen receptor expression may alter the prostate cancer cells' response to its ligand or even its antagonists." (PMID 18986533, 2008). "However, androgen and the androgen receptor (AR) are postulated to play crucial roles in the development of prostate cancer." (PMID 18798984, 2008). "Furthermore, an inverse correlation between androgen receptor (AR) status and NFκB activity was observed in prostate cancer cell lines." (PMID 18226269, 2008). "Moreover, recent laboratory studies similarly confirm ligand-independent activation of the AR through HER2 in prostate cancer cells." (PMID 18334972, 2008). "The inhibition of AR expression and signalling suggest a mechanism by which 25-OCH3-PPD could reduce the risk for development of prostate cancer and function in the treatment of both androgen-dependent and androgen-independent prostate cancer." (PMID 18253123, 2008). "In addition, interaction between β-catenin and the androgen receptor (AR) has been shown to enhance AR-mediated transcription, which plays a critical role during prostatic cancer progression." (PMID 18478098, 2008). "In addition to its role in AIS, AR is important in prostate cell proliferation, differentiation and survival, and plays at least a permissive role in development of prostate cancer." (PMID 18978937, 2008). "Prostate carcinomas are initially androgen-dependent (ADCaP) and hormone ablation efficiently inhibits their growth, although some deleterious side effects result from the inhibition of AR signaling in normal tissues." (PMID 17925854, 2007). "In fact, hormone-refractory prostate cancer cells often can maintain functional AR signaling despite greatly reduced levels of circulating testosterone as, for instance, with orchiectomy because of AR overexpression." (PMID 17384772, 2007). "Thus, there is significant evidence that BPA can bolster AR-T877A activity and as a result potentially alter the course of therapeutic response in prostate cancer." (PMID 18007998, 2007). "Thus, a “by-pass” of the requirement for androgen to interact with AR for activation of downstream events can occur in prostate cancer with acquired androgen independence." (PMID 17384772, 2007). "Because decursin and DA potently inhibit the cytosol to nuclear translocation of AR upon androgen stimulation in prostate cancer cells, we investigated whether a similar inhibitory effect was exerted on ERα." (PMID 17986353, 2007). "In support of this possibility, a recent study using a dual EGFR/HER2 kinase inhibitor in prostate cancer cell lines showed that an HER2/ERBB3 signalling pathway protected the AR from degradation at low androgen concentrations through an AKT-independent pathway." (PMID 17211467, 2007).
prostate carcinoma (continued). "Taken together, our results provide evidence for linking DDC action with AR signaling, which may be important for orchestrating molecular changes responsible for prostate cancer progression." (PMID 17553164, 2007). "Several reports have described the involvement of HER-2/neu tyrosine kinase—a type I growth factor receptor tyrosine kinase—in activating the AR through the MAPK pathway, and HER-2/neu expression has been implicated in the progression of prostate cancer to a hormone independence." (PMID 17384772, 2007). "In the case of prostate cancer, one mechanism could be through the ability to directly repress AR activity or sequester it from its nuclear targets." (PMID 17375037, 2007). "22Rv1 cells are androgen-independent prostate cancer cells that express the AR-H874Y mutant." (PMID 18007998, 2007). "Of note, however, is that a significant fraction of published microarray studies using the AR-dependent prostate cancer cell lines have been performed using high doses of androgen (≥10 nM), which induce profound cell cycle arrest in prostate cancer cells." (PMID 18007998, 2007). "The androgen receptor is a transcription factor, activated by the androgens testosterone and dihydrotestosterone and is responsible for development and maintenance of the function of the normal prostate and for growth of early stage prostatic cancer." (PMID 17233900, 2007). "The main goal of this study was to analyse whether the antiproliferative activity of RES in human prostate cancer cells could be mediated by inhibition of the AR- and ERα-dependent PI3K pathways." (PMID 17486135, 2007). "Altered regulation of this receptor in prostate cancer cells could lead to indirect activation of the AR signaling pathway." (PMID 17553164, 2007). "In the second evaluation experiment on microarray data, we used Anni for the analysis of the list of 221 differentially expressed genes as measured with a DNA microarray following the agonistic stimulation of the androgen receptor in a prostate cancer cell line." (PMID 17233900, 2007). "Moreover, the majority of studies have shown that recurrent, androgen-independent prostate cancer cells still require AR activity for proliferation and survival." (PMID 17375037, 2007). "Coregulator proteins play a crucial role in modulating transactivation of AR and consequently may be important in regulating aberrant activity of AR during prostate cancer progression." (PMID 17553164, 2007). "Our data show that docetaxel/trastuzumab combination caused a simultaneous hormone-receptor and HSP90 degradation and enhances the antitumour efficacy of docetaxel, suggesting that complete inactivation of AR could affect HID prostate cancers." (PMID 17211467, 2007). "Moreover, RES modulated the transcriptional activity of the AR in LNCaP prostate cancer cells, inducing changes in gene expression that were similar to those observed after inhibiting the transcriptional activity of the ERα in MCF-7 breast tumour cells." (PMID 17486135, 2007). "Importantly, we observed that AR silencing reduced the VEGF synthesis in LNCaP as well as in C4-2 and 22RV1 cells, demonstrating that VEGF is still regulated by AR in advanced prostate cancers." (PMID 17925854, 2007). "Amplification of the AR gene is rarely identified in untreated cases of prostate cancer." (PMID 19675761, 2007). "The AR may also contribute to prostate cancer growth during its recurrence in the androgen-deprived patient." (PMID 17367528, 2007). "In addition to the effects on proliferation, previous data in prostate cancer cell lines suggest that cyclin D1 has specialised roles concerning AR function in the control of prostate cancer cellular function." (PMID 17375037, 2007). "Based on this hypothesis, one might speculate that specific contextual variables (e.g. AR expression and dependence) may distinguish cyclin D1b action in individual cell types (e.g. prostate cancer cells versus NIH3T3 cells)." (PMID 16863592, 2006).
prostate carcinoma (continued). "The net result of these actions is down-regulation of AR function, as demonstrated by slowed cell cycle progression and down-regulation of endogenous PSA (prostate specific antigen) expression, an AR target gene utilized clinically to monitor prostate cancer growth and recurrence." (PMID 16863592, 2006). "For AR, it has been established that cyclin D1b is significantly altered in its ability to modulate receptor function, and this disparate action has consequence in prostate cancer cells." (PMID 16863592, 2006). "Although this polymorphism is associated with AR transactivation activity and prostate cancer risk in some studies, no clear association has been shown with breast cancer risk." (PMID 16987421, 2006). "The androgen dependence of prostate cancer cells is exploited in treatment of disseminated prostate cancers, wherein ablation of AR activity (through either ligand depletion and/or through the use of AR antagonists) is the first line of therapeutic intervention." (PMID 16863592, 2006). "AR stimulates prostate cancer cell growth through its ability to stimulate gene expression." (PMID 16863592, 2006). "Thus, evidence suggests that altered AR levels, activity, or function can play a major role in the development of androgen-refractory prostate cancer cells, although an AR bypass can also be important." (PMID 16140617, 2005). "The fact that inhibition of expression of Ebp1 leads to increased transcriptional activation of AR suggests that endogenous Ebp1 may function to regulate AR signalling in prostate cancer cells." (PMID 15583694, 2005). "In the presence of low concentrations of HRG, such as has been observed in prostate cancer tissues, the activity of Ebp1 may be suboptimal, resulting in increased AR signalling." (PMID 15583694, 2005). "One explanation for this may be that receptors other than the androgen receptor may be more important than previously appreciated in determining prostate cancer responses." (PMID 15570307, 2005). "We were interested in determining if Ebp1 represses wild-type AR in prostate cancer cell lines." (PMID 15583694, 2005). "In many human prostate cancers, overexpression of the androgen receptor has been noted." (PMID 15647107, 2005). "AR amplification is found in approximately 30% of clinically advanced prostate cancer cases." (PMID 16140617, 2005). "However, it is the pivotal role of AR in the development and progression of prostate cancer that has led to increasing interest in this nuclear receptor." (PMID 15328534, 2004). "While naturally occurring mutations in AR have yet to be observed at Met734, it is interesting to note that mutations at Val730 and Ile737 have been reported in patients with prostate cancer and androgen insensitivity, respectively." (PMID 15328534, 2004). "Therefore, increased androgen receptor expression, by whatever mechanism, can at best only explain hormone resistance in a subgroup of prostate cancer cases." (PMID 12888829, 2003). "Both studies are important in that they demonstrate increases in AR mRNA in prostate cancers." (PMID 12888829, 2003). "It is hypothesised that AR gene amplification is involved in the development of hormone-resistant prostate cancer due to amplification, resulting in an increase in AR protein expression." (PMID 12888829, 2003). "We conclude that RAC 3 is an important co-activator of the AR in the prostate and may have an important role in the progression of prostate cancer." (PMID 11747336, 2001). "We conclude that short CAG repeats in the AR gene correlate with young age at diagnosis of prostate cancer, but not with higher risk of the disease." (PMID 10574254, 1999). "Advanced prostate cancer is treated by androgen ablation and/or androgen receptor (AR) antagonists." (PMID 10496349, 1999).